INS (insulin)
Diseases named in the same sentence as INS in open-access papers (continued):
Sharing a sentence is not in itself a finding about the gene and the disease.
diabetic ketoacidosis (continued). "Diabetic ketoacidosis was detected, which was treated by controlling the blood glucose level stringently via intravenous insulin infusion." (PMID 38649870, 2024). "Diagnostic confirmation is usually based on glycated hemoglobin (HbA1c) testing, age at diagnosis, response to insulin, presence of diabetic ketoacidosis symptoms, and underweight." (PMID 39303284, 2024). "By hospital day 2, the patient was managed in the ICU with serial labs, titrated insulin administration, vigilant electrolyte replacement, and judicious volume management until the resolution of diabetic ketoacidosis." (PMID 39781139, 2024). "In diabetic ketoacidosis, high levels of ketones are produced in response to low insulin levels and high levels of counterregulatory hormones." (PMID 38535328, 2024). "While treatment was initially well tolerated, after three infusions, the patient was diagnosed with diabetic ketoacidosis, and insulin therapy was started." (PMID 38596681, 2024). "The family group had consulted earlier (p < 0.001), were less in initial diabetic ketoacidosis (p = 0.016), and had a lower HbA1C level lower (p < 0.001) and lower initial insulin requirements (p < 0.001)." (PMID 38860082, 2024). "The proband in Case 3 was also initially diagnosed with T1DM and was started on insulin therapy, as he presented with classic features of diabetic ketoacidosis." (PMID 39420905, 2024). "This feasibility study aimed to investigate the use of exhaled breath analysis to capture and quantify relative changes of metabolites during resolution of acute diabetic ketoacidosis under insulin and rehydration therapy." (PMID 38752172, 2024). "Results & conclusion: The present study establishes that a low insulin dose exhibits comparable efficacy to the standard dosage for managing pediatric patients suffering from diabetic ketoacidosis, with a lower incidence of complications." (PMID 38827803, 2024). "In this report, we present a case of a patient undergoing EV treatment for urothelial carcinoma who developed refractory diabetic ketoacidosis (DKA) unresponsive to escalating insulin doses and necessitating continuous renal replacement therapy." (PMID 38425338, 2024). "For patients progressing to diabetic ketoacidosis, the insulin injections and aggressive fluid resuscitation are also necessary." (PMID 38681048, 2024). "One rarely reported adverse effect has been life-threatening diabetic ketoacidosis (DKA) driven by profound insulin resistance." (PMID 39588551, 2024). "A specific study on diabetic ketoacidosis patients indicated that a combination of intravenous insulin and subcutaneous glargine showed a trend towards faster resolution and shorter hospital stays, though statistically insignificant." (PMID 38330019, 2024). "Diabetic ketoacidosis usually occurs due to absolute or relative insulin lack accompanied by increased glucagon, cortisol, growth hormone, and epinephrine." (PMID 37363479, 2023). "The patient was treated for diabetic ketoacidosis using intensive insulin therapy protocol, and the nodules were surgically excised." (PMID 38022190, 2023). "Studies evaluating patients presenting with diabetic ketoacidosis showed that a substantial proportion had retained C-peptide at follow-up and were able to successfully stop insulin therapy." (PMID 36355183, 2023). "This retrospective cohort study evaluated patients with diabetic ketoacidosis who received intravenous regular human insulin infusion during the COVID-19 pandemic." (PMID 36741601, 2023). "Most (78.3%) ICI-DM patients were treated with anti-PD-1, 78.3% presented with diabetic ketoacidosis, and all had low C-peptide levels and received multiple insulin injections." (PMID 37359544, 2023). "Just 2 days after stopping insulin therapy alone, the patient was readmitted to hospital with diabetic ketoacidosis." (PMID 37960733, 2023).
diabetic ketoacidosis (continued). "Among the immediate treatment options for severe diabetic ketoacidosis is a multidisciplinary approach that emphasizes correcting fluid and electrolyte imbalances, restoring insulin sensitivity, and preventing complications." (PMID 37363479, 2023). "Four patients had diabetic ketoacidosis, requiring insulin therapy based on the standard diabetic ketoacidosis protocol." (PMID 38192935, 2023). "Two days before admission, his wife was unable to administer insulin due to excessively high glucose levels, which were displayed as “high” on the patient’s glucose meter; therefore, we diagnosed the patient with diabetic ketoacidosis." (PMID 35033005, 2022). "Intravenous (IV) insulin infusion is the standard of care for treating diabetic ketoacidosis (DKA) worldwide." (PMID 36066894, 2022). "In PWT1D, it is recommended to start insulin treatment immediately after clinical diagnosis, to prevent metabolic decompensation and diabetic ketoacidosis." (PMID 36510287, 2022). "In this meta-analysis, the Overall use of IV insulin in patients with mild/moderate vs. severe diabetic ketoacidosis was compared in randomized controlled trial articles from January 2011 to December 2021 using EMBASE, Medline, and CENTRAL." (PMID 36439560, 2022). "Only two subjects (8.7%) experienced transient grade 4 TRAEs, of which one developed diabetic ketoacidosis after radical surgery and resolved within a week with active insulin and supporting treatment." (PMID 36224603, 2022). "After insulin treatment, diabetic ketoacidosis was cured and blood glucose was controlled satisfactorily." (PMID 35346144, 2022). "Detailed forest plots outlining the effect size of intravenous insulin in Diabetes Ketoacidosis in Plasma glucose, pH, Potassium levels, and time to resolution of acidosis are provided in the manuscript." (PMID 36439560, 2022). "Lipohypertrophy is a complication of insulin injection therapy, leading to erratic systemic absorption of insulin and contributing to the development of diabetic ketoacidosis." (PMID 36415718, 2022). "Intravenous insulin administration is the preferred method of administering insulin to individuals with diabetic ketoacidosis (DKA)." (PMID 36439560, 2022). "The patient with diabetic ketoacidosis was admitted due to poor compliance with insulin treatments and had a complicated hospital course with severe acidosis, changes to glucose and potassium levels, dehydration, and chemotherapy-related neutropenia." (PMID 36280642, 2022). "What is the cost-effectiveness of subcutaneous (SC) insulin aspart compared with standard-of-care intravenous insulin infusion in treating children with mild uncomplicated diabetic ketoacidosis (DKA)?" (PMID 36066894, 2022). "This cohort study assesses outcomes after implementation of a subcutaneous insulin protocol for treating diabetic ketoacidosis." (PMID 35389497, 2022). "Based on the findings mentioned, IV insulin is safe and effective in mild/moderate and severe cases of diabetic ketoacidosis (DKA)." (PMID 36439560, 2022). "The patient was rehydrated and started on insulin infusion according to the diabetic ketoacidosis protocol following the diagnosis of euglycemic diabetic ketoacidosis." (PMID 35346357, 2022). "Patients with higher serum C-peptide required lower doses of insulin and had fewer events of diabetic ketoacidosis." (PMID 35518934, 2022). "Intravenous insulin is one method of managing diabetic ketoacidosis, although there is limited data on its effectiveness and safety in treating diabetic ketoacidosis patients." (PMID 36439560, 2022). "Recent data suggest that SARS-CoV2 infection can lead to a deterioration in glycemic control, involving both profound insulin resistance, and impaired insulin secretion, together with leading to diabetic ketoacidosis, DKA." (PMID 35077488, 2022). "At admission, he was in diabetic ketoacidosis, and treatment with fluid infusion rehydration and then i.v. insulin was required." (PMID 36078750, 2022).
diabetic ketoacidosis (continued). "Intravenous insulin is reserved for use in treatment of diabetic ketoacidosis, during major surgery, and in critical illness." (PMID 37745178, 2021). "Alcohol, cocaine, marijuana, and methamphetamine use have been linked to diabetic ketoacidosis (DKA), possibly due to insulin omission while using these substances versus a direct impact on insulin secretion and glucose metabolism." (PMID 34912300, 2021). "On physical examination, he was found to have dry oral mucosa with poor skin turgor, with diagnostics showing that he was in diabetic ketoacidosis after running out of insulin for 2 days." (PMID 34044882, 2021). "When reducing the dosage of insulin, adjustment by within 10–20% of the total insulin dose is recommended to avoid development of diabetic ketoacidosis." (PMID 32403420, 2020). "Is subcutaneous administration of rapid-acting insulin as effective as intravenous insulin for treating diabetic ketoacidosis?" (PMID 31692874, 2019). "R3.3—Low continuous intravenous insulin doses should probably be administered in the treatment of diabetic ketoacidosis (GRADE 2+, STRONG AGREEMENT)." (PMID 31418093, 2019). "Four controlled and randomized trials compared subcutaneous (SC) insulin with intravenous (IV) insulin in management of diabetic ketoacidosis in adults." (PMID 31418093, 2019). "Rationale Two literature reviews have considered the optimal route for administration of insulin in diabetic ketoacidosis." (PMID 31418093, 2019). "A 28-year-old Japanese woman developed diabetic ketoacidosis and received insulin therapy after bone marrow transplantation." (PMID 30545408, 2018). "When she was 19 years of age, she developed diabetic ketoacidosis and started insulin injection therapy." (PMID 30545408, 2018). "The strongest support for the traditional belief was from demonstrations of missing or inappropriately low secretion of insulin in patients with diabetic ketoacidosis and the observation of immediate relief of the condition upon insulin administration." (PMID 28323959, 2017). "Supplementation of insulin can inhibit lipolysis and ketone production, as well as decrease glucagon secretion, and is thus the main treatment for diabetic ketoacidosis." (PMID 29258472, 2017). "Guidelines for the management of adult diabetic ketoacidosis still include administration of IV insulin bolus and sodium bicarbonate." (PMID 28321786, 2017). "This is exemplified in recent work demonstrating that many hospitals require ICU admission for individuals with diabetic ketoacidosis requiring continuous insulin infusion." (PMID 27898697, 2016). "Intravenous infusion of insulin was previously used to achieve glycaemic target for patients in the Intensive Care Unit and those with diabetic ketoacidosis due to the rapid action and shorter half-life." (PMID 26697503, 2016). "More than 1/3 of the nurses considered themselves to have inadequate knowledge about diabetic ketoacidosis, mechanisms of drug action, types of insulin, HbA1C, and special issues (Table-II)." (PMID 26150859, 2015). "An effective diet and exercise plans including an increased insulin infusion dosage will be the right medication strategy for the treatment of catamenial diabetic ketoacidosis as well as for avoiding any diabetic emergencies." (PMID 26273667, 2015). "We excluded a large number of patients, including those with diabetic ketoacidosis or who were supported with eProtocol-insulin for <1 day." (PMID 24886864, 2014). "We studied critically ill patients from eight hospitals, excluding patients with diabetic ketoacidosis and patients supported with eProtocol-insulin for < 24 hours or with < 10 glucose measurements." (PMID 24886864, 2014). "Diabetic ketoacidosis was diagnosed and was managed with an insulin drip and aggressive fluid resuscitation." (PMID 22839997, 2012).
diabetic ketoacidosis (continued). "Cholesteryl ester ratio method has also been successfully used to monitor the delay of OS recovery in patients with diabetic ketoacidosis after correction of ketoacidosis with insulin." (PMID 21829457, 2011). "The aim of the study was to evaluate the changes of the plasma GLP−1 and GLP−2 levels before and during insulin treatment in diabetic ketoacidosis (DKA) which is a state characterized by extreme insulin deficiency." (PMID 21274399, 2009). "Therapy with intravenous insulin resulted in resolution of the diabetic ketoacidosis and resolved the petechial rash of both legs." (PMID 23675135, 2009). "The patient was felt to be in diabetic ketoacidosis and was started on intravenous insulin and isotonic saline infusions to which he responded well with rapid resolution of the acidosis and abdominal pain within ten hours." (PMID 18267031, 2008). "Diabetic ketoacidosis, if treated with insulin and fluid, can be resolved, and while there may be lingering effects, in most cases, a child can recover." (PMID 41597086, 2026). "In clinical trials, GLP-1RAs used alongside automated insulin delivery systems demonstrate significant improvements in weight, glucose sensor time-in-range, and total daily insulin dose, without increased risk of diabetic ketoacidosis (DKA)." (PMID 41889083, 2026). "Advances in insulin therapy have contributed to improved outcomes in diabetic ketoacidosis (DKA)." (PMID 40625476, 2025). "An increase in the dose of insulin was related to the severity of diabetic ketoacidosis." (PMID 40037551, 2025). "In our study, which included patients prescribed insulin, factors during the follow-up period, such as discontinuation of insulin, may have influenced the development of diabetic ketoacidosis." (PMID 40429346, 2025). "However, given the acute nature of diabetic ketoacidosis and its profound metabolic disturbances, we anticipate that the effects of ovulation-related insulin resistance would be minimal in comparison." (PMID 40700071, 2025). "In some reported cases diabetic ketoacidosis (DKA) has been treated with intravenous insulin and by reducing intravenous glucose infusion, but with non-univocal results; other authors described plasma glucose levels trending towards spontaneous normalization after treatment of the metabolic crisis." (PMID 41480351, 2025). "She developed abrupt-onset, insulin-deficient diabetes presenting as diabetic ketoacidosis, characterized by undetectable C-peptide and negative islet cell autoantibodies, while undergoing adjuvant immunotherapy for stage IIIC melanoma." (PMID 41018379, 2025). "The same may be true for some people with T1D who have difficultywith medication compliance and who experience recurrent diabetic ketoacidosis (DKA)because of inconsistent insulin administration." (PMID 38224978, 2024). "Coupled with the slightly disproportionate reporting of diabetic ketoacidosis associated with GLP-1 RAs when they occur without combination with insulin, there is a need to be concerned about ketoacidosis as a potential adverse effect when using GLP-1 RAs." (PMID 39040467, 2024). "However, despite this, parents felt that no matter what the CGM results showed, the knowledge would enable them to be more prepared, thereby, preventing possible complications such as diabetic ketoacidosis (DKA) or delays in starting insulin therapy." (PMID 39611061, 2024). "Most of the patients present with diabetic ketoacidosis characterized by absent C-peptide, causing the decline of the insulin production, as was observed in our patient." (PMID 39247185, 2024). "Specifically, patients treated with continuous subcutaneous insulin infusion have a greater risk of developing diabetic ketoacidosis because there is no subcutaneous depot of insulin, and therefore ketoacidosis can occur much faster." (PMID 38713496, 2024).
diabetic ketoacidosis (continued). "This resulted in glucose levels near diabetic ketoacidosis, delayed hospital discharge and caused women to have to administer their insulin from home without the knowledge of the healthcare team." (PMID 38163872, 2024). "Furthermore, our study found a strong association between TAC and diabetic ketoacidosis, likely due to TAC' toxic effects on pancreatic β-cells and inhibition of insulin secretion." (PMID 39840315, 2024). "Diabetic ketoacidosis at onset or after impaired delivery of insulin needs particular attention." (PMID 39519472, 2024). "All patients presented with diabetic ketoacidosis and required lifelong insulin therapy." (PMID 38681767, 2024). "The literature supports the use of insulin infusion over the subcutaneous route of insulin administration for several clinical indications, including diabetic ketoacidosis (DKA), critical care illness accompanied by hemodynamic instability, and postcardiac surgical procedures." (PMID 38698018, 2024). "It was found that mycophenolate mofetil could be used to treat T2DM and diabetic ketoacidosis and improve insulin resistance." (PMID 37189611, 2023). "In contrast, the average HbA1C of T2D progressors in this smaller cohort evaluated in the Prediabetes Clinic was 8.1%; only 1 patient (3%) presented with diabetic ketoacidosis, 6 patients (17%) required insulin, and 1 patient was prescribed a GLP1RA at diagnosis." (PMID 37841954, 2023). "Previous studies have stated that the administration of subcutaneous short-acting insulin analogues as an alternate approach, as they have been used for several years, successfully, in converting mild to moderate diabetic ketoacidosis in physiological conditions." (PMID 36839456, 2023). "Our goal is to use POCT result of potassium so we may start insulin infusion within five to 10 minutes of arrival of diabetic ketoacidosis (DKA) patients to the emergency room (ER)." (PMID 35371883, 2022). "The expression of the vitamin D receptor on pancreatic beta cells appears to have a role in insulin secretion, and low vitamin D levels could facilitate the onset of diabetic ketoacidosis." (PMID 36364863, 2022). "SGLT2 increases the concentration of ketone bodies and may lead to euglycemic diabetic ketoacidosis, particularly in patients who lack enough insulin in the system)." (PMID 35269954, 2022). "High levels of ketones are produced as a result of low insulin levels in diabetic ketoacidosis." (PMID 34562928, 2021). "Reduction in serum phosphate level during hospitalization can occur among patients who receive insulin for treatment of diabetic ketoacidosis, sepsis, alcoholism, urinary phosphate-wasting syndromes, malnutrition and refeeding syndrome, and postoperative patients." (PMID 33028266, 2020). "Baseline data, blood glucose (BG) and beta-hydroxybutyrate (BHB) concentration at admission and at “time zero” in dogs with diabetic ketoacidosis treated with IM insulin lispro (Group L) and treated with IV continuous rate infusion of regular insulin (Group R)." (PMID 33195532, 2020). "Strikingly, recent data suggest that SARS-CoV2 infection can lead to a deterioration in glycemic control, involving both profound insulin resistance (requiring as much as 50–100 U insulin/h) and impaired insulin secretion, together leading to diabetic ketoacidosis, DKA." (PMID 33133024, 2020). "Insulin therapy is the cornerstone of the treatment of diabetic ketoacidosis (DKA)." (PMID 33195532, 2020). "Diabetic ketoacidosis was previously reported to be associated with a decrease in arterial AcAc/β-HB ratio with a relatively high level of generation of β-HB, while insulin treatment decreases serum β-HB long before serum AcAc in diabetic ketoacidosis, resulting in an increased AcAc/ β-HB ratio." (PMID 33238897, 2020). "Diabetic ketoacidosis occurs in young subjects treated with insulin therapy." (PMID 31692874, 2019).